TNF (tumor necrosis factor)
Diseases named in the same sentence as TNF in open-access papers (continued):
Sharing a sentence is not in itself a finding about the gene and the disease.
COVID-19 (continued). "The results showed an elevated concentration of IL-1β, IL-6, TNF-α, IL-2R, IL-17, and IL-10 cytokines in the serum of COVID-19 patients." (PMID 35842705, 2022). "A different investigation with 21 COVID-19 cases found that severe cases had greater levels of IL-2R, IL-6, IL-10, and TNF-α than moderate cases." (PMID 36675695, 2022). "We identified that Preg-recovered COVID-19 women have reduced capacity for the inflammatory cytokine TNF-α from cytotoxic CD8+ T cells." (PMID 35647028, 2022). "Similar to COVID-19-related inflammation, CQ has shown rescuing effects against brain neuroinflammation by suppressing the inflammatory cytokines, such as TNF-α, IL-6, and IL-12, in LPS-challenged mice." (PMID 35455977, 2022). "In COVID-19 patients, IL-6 and TNFα are among the most important ones, given that their levels are strong independent predictors of patient survival." (PMID 35563218, 2022). "Pro-inflammatory signatures of severely affected COVID-19 patients feature elevations of interleukin-1β (IL-1β), IL-6, and tumor necrosis factor alpha (TNF-α)." (PMID 35600840, 2022). "Results of a cohort study showed that diminution of some bacterial species in patients with COVID-19 was connected to increase in the level of IL-10, TNF-α, CXCL10, and CCL2 and immunological responses." (PMID 35342407, 2022). "The interferon, interleukin, chemokines, and TNF were main factors of the development of cytokine storm for patients with COVID-19." (PMID 35911765, 2022). "Hitherto, no results from randomised controlled trials assessing the effectiveness and safety of infliximab—a monoclonal antibody targeting TNF-α—in the treatment of COVID-19 have been published." (PMID 36056419, 2022). "In the current study, it has been shown that testosterone levels were significantly lower in COVID-19 male patients compared to healthy controls, which is in parallel with the increased levels of TNF-α and IL-6 levels." (PMID 36381078, 2022). "Studies show that COVID-19 patients have increased levels of numerous inflammatory cytokines, like IL-1 beta, IL-2, IL-6, TNF-alpha, etc. and these cytokines correlate with disease severity." (PMID 35629072, 2022). "Three studies demonstrated a high proportion of CD14+ and CD16+ cells in patients with severe COVID-19, with inflammatory factors including GM-CSF and IL-6, IL-10 and TNF-α." (PMID 35843719, 2022). "The binding of TNFα to its receptor, hTNF1, plays an important role in the initiation of inflammatory cascades in COVID-19, which can lead to cytokine storm that is responsible for ADRS." (PMID 36574379, 2022). "Of note, the severity of pulmonary complications in COVID-19 seems to be closely related to IL-6 and TNF-α peak levels." (PMID 35211011, 2022). "In this respect, there is evidence that O2–O3 therapy can counteract chronic inflammation by reducing the circulating levels of the main pro-inflammatory cytokines IL-6, IL-2, IL-8, IFN-γ, TNF-α, and IL-1β in a variety of disease contexts, including COVID-19." (PMID 36140358, 2022). "Nevertheless, increased expression of NKG2A led to the reduced levels of CD107a (degranulation marker), IFN-γ, IL-2, granzyme B, and TNF-α in NK cells from COVID-19 patients." (PMID 36505489, 2022). "Our data showed that the hIL-7-Fc–containing supernatant harbored the capacity to restore the production of IFN-γ and/or TNF-α cytokines by T lymphocytes from both patients with septic shock and COVID-19." (PMID 36045686, 2022). "Several pro-inflammatory proteins, such as CXCL-10, IL-6, IL-10, IL-12, and TNF, have been identified to be upregulated in severe COVID-19 patients." (PMID 35251030, 2022). "Recent evidence proposed that the severity of the coronavirus disease 2019 (COVID-19) in patients is a consequence of cytokine storm, characterized by increased IL-1β, IL-6, IL-18, TNF-α, and IFN-γ." (PMID 36111104, 2022).
COVID-19 (continued). "Flow cytometry based study on monocytes from patients with severe COVID-19 demonstrated elevated levels of IL-6, IL-1, and TNF-α, indicating an inflammatory monocyte phenotype." (PMID 35601440, 2022). "(2020) noted that elevated serum levels of IL-6, IL-8, and TNF-α in COVID-19 patients at the time of hospitalization were strong and independent predictors of patient survival." (PMID 35846757, 2022). "These immune cells can release a large amount of pro-inflammatory cytokines (IL-1β, IL-6, TNF-α, IL-8), which is typical in COVID-19 patients." (PMID 36296527, 2022). "A computer model identified potentially beneficial drugs for critically COVID-19 patients that act by inhibiting the tumor necrosis factor (TNF)-induced NFkB1 signaling pathway, which is inhibited by APC activity." (PMID 36560757, 2022). "This review aims to discuss some roles of TNF and its receptors in the pro-inflammatory stage of COVID-19, understand its ways of action, and let to reposition this cytokine or some of its receptors as therapeutic targets." (PMID 35631442, 2022). "Severity of COVID-19 is correlated to the unique inflammatory profile of patients with high serum levels of multiple cytokines and chemokines/growth factors: TNF-α, IL-1, 6 and 12, IFN-gamma, and TGF-beta, CCL2, CXCL9 and 10, and IL-8." (PMID 35409070, 2022). "In the case of COVID-19, the production of inflammatory cytokines such as IL-6, IL-1, TNF-α, and CRP contributed to a storm of cytokines resulting in an immune dysregulation induced by T cells and inflammatory monocytes." (PMID 35685606, 2022). "Considering that COVID-19's cytokine storm presents with an elevation of IL-6, TNF-a, and IL-1ß and that pathophysiology of myalgia also involves these cytokines, it seems reasonable to associate SARS-CoV-2 infection with myalgia." (PMID 35223956, 2022). "TCD4/SARS-CoV-2 show lower polyfunctional capacity (INF-γ, IL-2 and TNF-α) in aTB/COVID-19 vs. COVID-19." (PMID 36090983, 2022). "This article will address the current understanding of cytokines-induced alterations in COVID-19, focusing on interleukin (IL)-6, IL-1, IL-17, and tumor necrosis factor (TNF)." (PMID 35619180, 2022). "Our data suggest an impairment of the antiviral inflammatory response mediated by IFN-γ and TNF-α in patients who died from COVID-19." (PMID 35336861, 2022). "In the current study, we performed direct comparisons of cytokine expressions in KD and severe COVID and found that the expressions of IL1A, IL1R1, and TNF were about 2.6- to 10-fold higher in severe COVID-19 than in KD." (PMID 36159873, 2022). "An increased expression of the inhibitory marker NKG2A results in the decreased level of IFNγ, IL-2, TNFα, CD107a and granzyme B in COVID-19 patients." (PMID 36369012, 2022). "Systemic inflammatory cytokine/chemokine response including TNFα, IL-6, MCP-1, IP-10, and MIP-1α has been associated with more severe disease in human studies of COVID-19." (PMID 35789343, 2022). "During the early stages of the pandemic, increased levels of many cytokines, including IL-6, IL-1β, TNF-α, and interferons, were observed in patients with COVID-19." (PMID 36289890, 2022). "Among COVID-19 patients, the most common disorders of cytokines and chemokines are increased levels of IL-1β, IL-2, IL-6, interleukin-7 (IL-7), IL-10, TNF-α, CRP, chemokine ligand 2 (CCL2), as well as an increase or decrease in the concentration of IFN-γ." (PMID 36294388, 2022). "An impairment in T-lymphocyte function, with reduced capacity to produce IFN-γ and TNF-α upon stimulation with anti-CD3/anti-CD28 monoclonal antibody has been evidenced in COVID-19 patients." (PMID 35207531, 2022). "Of these, TNF and IFN-γ are highly upregulated in the serum of patients with severe COVID-19 and TNF- and IFN-γ-induced cell death can lead to systemic inflammation, tissue damage, multiple organ failure, and death of COVID-19 patients." (PMID 35774397, 2022).
COVID-19 (continued). "Recovered individuals still maintain elevated levels of IFN-γ and TNF-α compared to symptomatic and dead patients from COVID-19." (PMID 35336861, 2022). "Furthermore, a T-cell response characterized by a limited expression of IFN-γ, low levels of polyfunctional T-cells, and high levels of monofunctional T-cells producing TNF-α has been associated with COVID-19 severity, suggesting that in PLWH, the coinfection could exacerbate COVID-19 pathology." (PMID 36499317, 2022). "Statins inhibit NLRP3 inflammasome activation by suppressing the oxidized LDL, and TNF α, and improving the cardiovascular functional outcomes in COVID-19 patients." (PMID 35865966, 2022). "Increased levels of IL-8, IL-6, monocyte chemoattractant protein-1, and TNF-α are observed in the plasma of COVID-19 patients." (PMID 36466841, 2022). "COVID-19 upregulates the expression of proinflammatory cytokines such as interleukin-6 and tumor necrosis factor-alpha, triggering a cytokine storm that recruits macrophages and causes inflammatory reactions." (PMID 35843961, 2022). "In this study of 90 ICU COVID-19 patients, we evaluated serum levels of four cytokines (IL-1β, IL-6, IL-10 and TNFα) as well as standard clinical and laboratory measurements." (PMID 36451808, 2022). "Use of LMWH was found to reduce serum IL-6 levels, which are a key factor in patients with severe COVID-19, and to reduce TNF-α levels." (PMID 34406312, 2022). "A third module (c) revolves around TNF and includes IL1A, IL1B, TNFSF14, TNFAIP3, and CSF2 that likely mediates the inflammatory response associated with COVID-19 progression." (PMID 35085325, 2022). "Several studies have demonstrated the presence of inflammatory mediators, such as increased levels of pro- and anti-inflammatory interleukins (IL-1, IL-2, IL-6, IL-10) and tumor necrosis factor-alpha (TNF-α) in the serum of COVID-19 patients." (PMID 36077138, 2022). "Levels of cytokines such as IL-6 and TNF-α increase rapidly, dysregulating the immune response and leading to direct myotoxicity in COVID-19." (PMID 36140656, 2022). "IL-18, along with other cytokines (IFN-γ, IL-1, IL-6, TNF), are elevated in cytokine storm and are thought to have central immunopathologic roles in COVID-19." (PMID 36510222, 2022). "Peripheral blood mononuclear cells (PBMCs) from COVID-19 patients released IL-1beta, IL-6, and TNF-alpha ex vivo." (PMID 36009328, 2022). "Symptomatic COVID-19 patients had significantly (p < 0.05) higher levels of IL-10, IL-2, IL-2R, IL-6, IL-8 GM-CSF IP-10, TNF-α, IL-4, IL-5, IL-12, IFN-γ and MIP-1β compared to the asymptomatic cases." (PMID 36184636, 2022). "Levels of interleukin TNF-α were reported in patients with severe COVID-19, although other reports suggest that other cytokines are involved in the pathogenesis of the illness." (PMID 37521833, 2022). "This review focuses on cytokine secretions of innate and adaptive immune responses against COVID-19, including interleukins, interferons, tumor necrosis factor-alpha, and other chemokines." (PMID 35464491, 2022). "The systemic inflammation elicited by COVID-19, increases the levels of several inflammatory molecules, including C-reactive protein, IL-1β, IL-2, IL-6, IL-8, IL-10, and TNF-α." (PMID 36439786, 2022). "The majority of upregulated cytokines and chemokines, such as IL-6, TNF, CCL2, CCL3, and CXCL10, have been reported to be associated with cytokine release syndrome (CRS), including MAS, in severe COVID-19 cases." (PMID 35440562, 2022). "Research on COVID-19 differentially expressed genes revealed that the TNF pathway is one of the mechanisms of pulmonary fibrosis secondary to COVID-19." (PMID 36339607, 2022). "Plasma levels of TNFα, IL-2, IL-6, IL-8, IL-10 (p < 0.001), IFNγ (p < 0.01), and GM-CSF (p < 0.05) were higher in COVID-19 patients compared to in HCs." (PMID 35625671, 2022).
COVID-19 (continued). "The cytosolic nucleic acids sensor LRRFIP1 mediates the production of type I interferon, which plays an important role in exacerbating TNF- and IL-1-driven inflammation in the progression to severe COVID-19." (PMID 35421082, 2022). "The increased inflammatory cytokines such as TNF-α and IL-6 induce apoptosis and necrosis in T cells, which are reduced in COVID-19." (PMID 35408447, 2022). "In patients recovering from mild COVID-19, there was a trend for higher IL-1β, IL-6, and TNF-α production." (PMID 35380990, 2022). "CXCL10, IL-17, and TNF-α, among the cytokines increased by COVID-19, have established roles in osteoblast proliferation and osteoclastogenesis, resulting in a reduced bone mineral density." (PMID 35159388, 2022). "IL-6, IL-8, IL-10, and TNF-α were increased in severe cases of COVID-19 while IFN-α, IL-1β, IL-4, and IL-15 were enriched in mild cases." (PMID 35685940, 2022). "After PWM stimulation, COVID-19 patients showed a reduced release of IFNγ, while IL-2 levels were found similar and TNF levels were increased compared to healthy controls." (PMID 36109525, 2022). "Therefore, two explanations may justify the increased PCT levels associated to severe COVID-19 outcome: first, the high serum levels of cytokines like IL-6 and TNF-α from “cytokine storm” that may promote the increase in PCT levels; second, the presence of a bacterial co-infection." (PMID 35355599, 2022). "Many cytokines have been reported to be increased in severe COVID-19 patients and a few of them, such as IL-6, IL-8, IL-10 and TNF-α, are considered to be indicators of severe disease." (PMID 35337002, 2022). "While the CD3+CD4+ and CD16+56+ lymphocyte counts are elevated in COVID-19 patients, TNF-α and IFN-γ decrease." (PMID 36423150, 2022). "More than 90% of COVID-19 studies (all but one) reported mean a TNF-alpha concentration lower than 10 pg/mL." (PMID 36289881, 2022). "Outbreaks of COVID-19 are accompanied by immunocompromised through hyperexpression of both proinflammatory (IL-1, IL-2, IL-6, and TNF-α) and anti-inflammatory (IL-4, IL-10, and IL-17) cytokines, and vice versa with IFN-γ." (PMID 36045713, 2022). "Inflammatory markers such as interleukine-6 (IL-6), IL-8, and tumor necrosis factor-alpha (TNF-α) have been detected in semen samples from individuals recovering or suffering from COVID-19." (PMID 35892675, 2022). "At the same time, Xiyanping injection inhibits the release of a variety of inflammatory factors by inhibiting intracellular MAPK, TNF, and other pathways and inhibiting NF-κB and other pathways in the nucleus, thus playing a role in the treatment of COVID-19." (PMID 35818408, 2022). "Similar to the BALF findings, the authors found that peripheral blood mononuclear cells (PBMCs) from COVID-19 patients exhibit a transcriptional upregulation of prototypical signaling ligands with known hDRG receptors, including IL-1β and TNF." (PMID 35281455, 2022). "Cytokine profiles of PBMCs showed significantly lower levels of GM-CSF, IFN-γ, IL-6, IL-9, IL-10, IL-17A, and TNF-α (p < 0.0001) in COVID-19 ICU patients." (PMID 36363785, 2022). "In agreement with their known roles as inducers and/or enhancers of NET formation, the plasma concentrations of IL-8 and TNFα correlated with those of both markers of NET production in the COVID-19 group." (PMID 36466824, 2022). "The literature identifies TNF-α and IL-6 receptor inhibitors to be effective in treating COVID-19 among patients with rheumatic diseases as during recovery of COVID-19, decreased levels of IL-6 and TNF-α increase the total T-cell counts." (PMID 35903564, 2022). "Given its multiple pro-inflammatory properties, TNF-α also has a strong rationale as a therapeutic target in COVID-19." (PMID 35208467, 2022). "We also described the correlation of inflammatory cytokine levels (resistin, IL-6, IL-8, IL-15, MCP-1 and TNF-α) with clinical variables related to a worse COVID-19 prognosis." (PMID 35330391, 2022).
COVID-19 (continued). "Regarding all these studies, it seems anti-TNF therapy can be accountable as a promising treatment for COVID-19 patients." (PMID 36574379, 2022). "Our results show a statistically significant decrease in TNF-α levels in serum, PBMCs, and neutrophils of COVID-19 ICU patients compared with healthy controls, suggesting an immunomodulatory effect of SARS-CoV-2 on TNF-α production by PBMCs and neutrophils." (PMID 36363785, 2022). "The same study revealed increased plasma concentrations of MCP-1 and TNFα in patients with COVID-19 admitted to the ICU." (PMID 35213582, 2022). "The decision of using AMDs in the treatment of COVID-19 was also supported by the anti-inflammatory activity and inhibition of the production of proinflammatory cytokines, such as tumor necrosis factor (TNF)-α and interleukin (IL)-6." (PMID 34218393, 2022). "In the present study, we measured the serum levels of TNF-related biomarkers in various severities of 80 hospitalized COVID-19 patients, of which 25 died during hospitalization." (PMID 36219652, 2022). "Patients with severe COVID-19 exhibit increased secretion of IL-2R, IL-6, and TNF-α, and elevated circulating levels of IL-6 and TNF-α are independent predictors of mortality." (PMID 35929616, 2022). "Irrespective of the memory phenotype, both Vδ1+ and Vδ2+ T lymphocytes of COVID-19 patients spontaneously produced TNF-α, IFN-γ, and IL-17, which are sustained after healing." (PMID 36359845, 2022). "Persistent proinflammatory cells [IL-1, IL-6, and Tumor Necrosis Factor-α (TNF-α)] and altered cytokine production is suspected to have occurred during persistent inflammation in post COVID-19 conditions, revealed by a cytokine profiling study." (PMID 36698905, 2022). "We performed quantitative real-time PCR (qRT-PCR) for representative COVID-19 related host inflammatory cytokine genes and found that a cytokine panel (including IL-6, IL-1β, TNF-α, CCL2, and CXCL9) was induced by SARS-CoV-2 infection." (PMID 34979342, 2022). "In order to add information on the regulation mechanisms between those cytokines, it would be useful to measure serum levels of IL-1 and TNF-α during the acute phase of COVID-19, testing their correlation with acute and post-acute VCAM-1 and IL-8 values." (PMID 36062000, 2022). "The identification of which COVID-19 patients are suitable for treatment with IL-6 antagonists and TNF-α inhibitor are meaningful in the clinic." (PMID 35237162, 2022). "From a cytokine perspective, IFN-γ and its synergism with TNF-α were thought to play a critical role in the pathogenesis of severe COVID-19 in CHIP (+) patients." (PMID 36229591, 2022). "An increase in pro-inflammatory Th17 cells and lymphopenia associated with decreased CD4+ T cells, CD8+ T cells, and natural killer cells, and increased cytokine levels (IL-6, IL-10, and TNF-α) were observed in COVID-19 patients." (PMID 36353605, 2022). "In the ongoing COVID-19 pandemic, damage to the mucosal barrier and immune cells due to the overproduction of pro-inflammatory (IL-1, IL-6, IL-12, IL-17, IFN-γ, TNFα) cytokines (cytokine storm) was evident in some COVID-19 patients." (PMID 36501067, 2022). "NLRP3 inflammasome activation primed and stimulated host inflammatory response, and the inflammatory cytokines (including IL-1β, IL-2, IL-6, IL-8, IL-18, and TNF-α) have been identified to be related to disease severity in COVID-19 patients." (PMID 34979342, 2022). "In summary, we found that ICU admission levels of serum IL-10 and TNFα were useful and statistically powerful prognostic markers for clinical outcomes in severe COVID-19." (PMID 36451808, 2022). "The TNF-α, NT-proBNP, albumin-to-globulin ratio, and CD4+ T-cells were also associated with an increased risk of death from COVID-19." (PMID 35453526, 2022). "While IFN-γ levels in NK cells significantly increased during progression of COVID-19 disease, levels of TNF-α remained high in all samples taken >11 days post onset of COVID-19 symptoms." (PMID 36275702, 2022).